SNORA50C (small nucleolar RNA, H/ACA box 50C)
Synonyms: ACA62; SNORA76; SNORA76C
Gene: Small nucleolar RNA gene on chromosome 17 (64,146,339 to 64,146,471, forward strand). Ensembl gene ENSG00000277887.
Gene Ontology:
Biological process: RNA processing
Cellular component: nucleolus
Homologues: Orthologues: chimpanzee SNORA50C (98% identical), dog SNORA50C (86% identical), rat Snora50c (85% identical), rabbit SNORA50C (83% identical), pig SNORA50C (82% identical), mouse Gm22711 (81% identical), guinea pig SNORA50C (80% identical). Paralogues in human: SNORA50D (79% identical), SNORA50B (58% identical), SNORA50A (56% identical).
Diseases named in the same sentence as SNORA50C in open-access papers:
SNORA50C is named in the same sentence as 1 disease in open-access papers, as found by Europe PMC text mining. Sharing a sentence is not in itself a finding about the gene and the disease.
SNORA50C shares sentences with these, for which no sentence is quoted: lung carcinoma (1 paper).